CXCL2 (C-X-C motif chemokine ligand 2)
Diseases named in the same sentence as CXCL2 in open-access papers (continued):
Sharing a sentence is not in itself a finding about the gene and the disease.
infection (continued). "CXCL2 and IL-8 are pro-inflammatory chemokines that assist in the mediation of neutrophil migration as well as the migration of other cellular and humeral factor components to the site of an infection." (PMID 24936153, 2014). "In aggregate, these findings indicate that CCR2 depleter mice produce wild-type levels of CXCL1 and CXCL2 during respiratory fungal infection and display preserved neutrophil recruitment to the site of infection, though these processes per se are insufficient to prevent the development of IA." (PMID 24586155, 2014). "IL-8 and CXCL2 are chemoattractants known to attract PMN to a site of infection." (PMID 24633052, 2014). "Indeed, MyD88-deficient mice lack the production of neutrophil chemokines (CXCL1, CXCL2) at the infection site." (PMID 25084278, 2014). "We also measured CXCL1 and CXCL2 levels at the site of infection." (PMID 25084278, 2014). "An increase in mRNA levels for a number of host immunomodulatory genes, including chemokines, CCL3, CCL5 and CXCL2 was observed at 4 h post-infection compared to mock-infected cells and a reduction to similar levels as in mock-infected cells at 16 h post-infection." (PMID 23265239, 2013). "In addition our study reveals elevated TNF and CXCL2 at 24 hours post-infection in Nlrc4−/−/Tlr5−/− mice compared to Nlrc4−/− and WT mice." (PMID 23937571, 2013). "Targeted deletion of Cxcl2 in mice does not cause congenital anomalies but does result in poor wound healing and increased susceptibility to infection." (PMID 21936905, 2011). "CXCL2, a chemokine related to preferential recruitment of neutrophils, was increased at 3 and 6 days p.i., indicating the presence of stimulus for leukocyte recruitment during the course of the infection." (PMID 21388530, 2011). "Infection of a confluent monolayer of intestinal epithelial m-ICcl2 cells with wild-type (wt) L. monocytogenes induced rapid cellular activation illustrated by secretion of the proinflammatory chemokine Cxcl-2." (PMID 21124989, 2010). "This conclusion is supported, at least in part, by the results of Sukumaran and colleagues, who reported the upregulated expression of chemokine genes encoding CXCL1, CXCL2, CXCL3, CXCL8, CCL3, CCL4 and CCL20 after infection of PMN with Anaplasma phagocytophilum." (PMID 17875202, 2007). "Furthermore, during severe infection, decreased CXCL2 expression in the spleen and downregulation of apoptosis-related genes suggest that LMBV may facilitate immune evasion by suppressing host defense mechanisms." (PMID 41009378, 2025). "This altered response was associated with increased gene expression of neutrophil chemokines Cxcl1 and Cxcl2 in whole lung homogenates, elevated concentrations of circulating granulocyte-colony stimulating factor (G-CSF), and higher neutrophil numbers in the lung 24 hours after infection." (PMID 35603143, 2022). "Flow cytometric analysis of infected lung tissue showed a nearly complete absence of neutrophil influx during the early infection phase (10 dpi) which can be linked to the downregulation of Cxcl5 and lack of Cxcl1 and Cxcl2 upregulation responsible for neutrophil chemotaxis during inflammation." (PMID 36400767, 2022). "Of these, a lncRNA, named NR_045064, could reduce infection burden of parasites in murine intestinal epithelial cells in vitro and in the enteroids of neonatal mice by promoting expression of host defense genes (e.g. Csf2, Nos2, and Cxcl2)." (PMID 35999576, 2022). "Our results show that ethanol-exposed mice had a higher pulmonary bacterial burden at 24 hours after infection despite increased numbers of pulmonary neutrophils and correspondingly higher expression of chemokines involved in neutrophil recruitment, such as Cxcl1 and Cxcl2." (PMID 35603143, 2022).
infection (continued). "Hence, we quantified the expression of various immunity-related genes regulated by NF-κB: IFNß, CXCL2, TNF, CCL5 and CXCL10 in the brain of mice from two genetic backgrounds, at late stage of the infection by Tha or the isogenic Th4M virus mutated on the positions 77, 100, 104, 110 of the M protein." (PMID 29084252, 2017). "In addition to G-CSF in MDSC recruitment from bone marrow, other studies have also demonstrated that chemokines CXCL1 and CXCL2 could promote the recruitment of MDSCs to the spleen during infection and inflammation." (PMID 26797765, 2016). "Consistent with clinical observations, in vitro infection of RD cells and in vivo infection of suckling mice in our study similarly demonstrated significant upregulation of IL-6, TNF-α, CXCL2, CXCL3, CXCL8 (IL-8), and CXCL10." (PMID 40872743, 2025). "SGE-enhanced dissemination of virus to joint tissues resulted in higher upregulation of key arthritogenic cytokine transcripts, including TNF-alpha and IL-6, and the chemokines CXCL2, CCL2, and CXCL10 at day 7 post infection." (PMID 41362756, 2025). "Our results showed that alveolar concentrations of CXCL1 and CXCL2 were indeed reduced in animals treated with SRT1720, as early as 24 h post-infection." (PMID 41096578, 2025). "In lung tissue, IL1B, IL6, IL10, CXCL2, CCL3 and CCL5 levels also rose in both genotypes following infection, although these markers were significantly lower in TLR7 KO mice." (PMID 40442368, 2025). "In comparison to uninfected mice, the levels of IL-1β, IL-6, IL-12p70, TNF-α, CCL2, CXCL2, GM-CSF, and G-CSF were significantly increased in both PLF and serum after infection." (PMID 38951957, 2024). "Numerous proinflammatory cytokines exhibited decreased expression in Omicron-infected BSs compared to those infected with the WT virus, including IL6, CXCL1, CXCL2, and IL1B, which play a crucial role in attracting immune cells to infection sites." (PMID 38741604, 2024). "We selected five cytokines, including CXCL-1, CXCL-2, IL-6, IL-8, and CCL-20, and determined their expression levels 24 h after infection using qPCR." (PMID 38756230, 2024). "Upon infection, macrophages produce mediators (CXCL1 and CXCL2) to recruit neutrophils to the site of infection and crosstalk between these two cell populations is key for the clearance of M.tb." (PMID 39649174, 2024). "We found that TNF-α, IL-β, CXCL2, TLR4, and IL-6 (mRNA) and selected proteins (TNF-α, IL-1β, and CXCL2) were upregulated significantly by exposure to the particulate and infection." (PMID 38928968, 2024). "In vivo experiments in mice of catheter-induced S. aureus infection showed a significant reduction in cytokine secretion of IL-1β, TNF-α, CXCL2, and CCL2 during biofilm infection." (PMID 38571946, 2024). "Using qPCR, we evaluated the expression of cytokines that are important for neutrophil recruitment to sites of infection, including IL1β, IL-6 and TNFα, as well as the neutrophil chemokines CXCL1 and CXCL2." (PMID 39509414, 2024). "The observed infiltration of immune cells after infection with swH1N1 agrees with the upregulation of chemotactic factors (AMCF-II, CXCL8/IL8, CXCL2, CXCL10, and CCL20) and their receptors (CCR1 and CXCR2) at the transcriptional level." (PMID 39247193, 2024). "Expression of IL-6, IL-8 (CXCL8), CXCL1, CXCL2, and CCL-20, which are known to be expressed in the respiratory epithelium upon infection, was assessed." (PMID 38756230, 2024). "Exposure to PM10 followed by infection significantly elevated relative mRNA levels for TNF-α, IL-1β, CXCL2, TLR4, IL-6, COX2, and iNOS when compared to control air (p < 0.001 for all)." (PMID 38928968, 2024). "PM10 exposure followed by infection significantly increased the protein levels of TNF-α (A), IL-1β (B), and CXCL2 (C), and decreased GPX4 (D) and Nrf2 (E) (p < 0.001 for each)." (PMID 38928968, 2024).
infection (continued). "Infection of BMDCs with EBs opsonized with male IgG enhanced expression of chemokines CXCL1, CXCL2, CXCL5 and pro‐inflammatory cytokines TNF, IL1β and IFNγ compared to uninfected or non‐opsonized controls." (PMID 38441219, 2023). "Expression of other genes that were strongly upregulated after infection with most mycobacteria included SERPINB1, CXCL2, CXCL8, CXCL10, and LCN2." (PMID 37822359, 2023). "CXCL2 and CXCL9 in chemokine were 957.6-fold and 128.5-fold upregulated in the spleen at 48 h of infection; by 96 h, the higher expression levels were CsCCL21.2, TroCCL4.2, and CsCCK1." (PMID 37888440, 2023). "While IL-6, IRF4, IRF6, and CXCL2 were significantly unchanged, TNF-α was significantly elevated in the infection-derived EVs at both 48 h and 72 h when compared to the control-derived EVs (* p = 0.01 and * p = 0.02, respectively) (respectively)." (PMID 36979955, 2023). "After infection or injury, mast cells and macrophages synthesize and release the neutrophil chemokine CXCL1/CXCL2 (CXC chemokine ligand 1/2) to trigger the early stage of neutrophil recruitment in response to inflammation." (PMID 37266443, 2023). "Similar to 12 h, genes significantly upregulated in the later stages of infection were cytokines or chemokines, such as CXCL1, CXCL2, CXCL3, CXCL8, CXCL10, and CCL20." (PMID 37211158, 2023). "Before infection, the latent condition presented the chemokine panel with near-high levels of CXCL11 and mild or moderate levels of CXCL2, CCL4, CCL2, CCL1, and CXCL9." (PMID 37149713, 2023). "In response to ocular HSV-1 infection, pro-inflammatory cytokines including IL-1, IL-6 and chemokines including CCL2, CCL3, CCL5, CXCL1, CXCL2, CXCL9, and CXCL10 are produced rapidly following infection by resident cells and infiltrating leukocytes." (PMID 36685562, 2022). "Cytokines in the brain (TNF-α, CCL-2, CXCL-2, CXCL-10, IL-1β, IL-6, IL-17, and M-CSF) were upregulated after infection at 3 dpi, and the cytokine content gradually decreased with extension of the infection time." (PMID 36352407, 2022). "In both iBEC-LMC and iBEC monocultures, CXCL8, CXCL1, CXCL2, and CCL20 were upregulated during the time course of infection, with higher upregulation of CXCL8 and CXCL1 in the monoculture model at 24 h p.i.." (PMID 36289516, 2022). "Neutrophils accumulated in the lungs of aged mice as early as day 1 post-infection, and this increase was maintained throughout the course of infection as compared with young mice and correlated with higher pulmonary CXCL1 and CXCL2 levels." (PMID 36233146, 2022). "In the stomachs of immunized mice after infection with H. pylori SS1, the expression of CXCL2 increased two-fold while the expression of the remaining genes did not change." (PMID 36466847, 2022). "IAV, or more precisely the NS1 of IAV, decreases the immune response in the lung to infection with this virus and thus decreases the expression of CXCL1/KC and CXCL2/MIP-2 there." (PMID 36613652, 2022). "As expected, SARS-CoV-WT infection induced at 2 days p.i. in the lungs a significantly higher expression of proinflammatory cytokines (CXCL10, CXCL2." (PMID 35229638, 2022). "Many chemokines are produced during the infection process, and specific cell types are recruited through several unique chemokine receptors, such as CXCL1, CXCL2, and CXCL8, which can recruit neutrophils." (PMID 35493728, 2022). "A more detailed analysis of DEGs indicated on a strong immune response in MKN-28 cells after 2-h infection based on increased transcription of IL1A, IL8, IL24, CXCL2, CXCL3 and CCL20." (PMID 37193047, 2022). "Several chemokines potentially attract neutrophils during an infection and S. suis infection induces the production of many of them, such as CXCL1 (KC), CXCL2 (MIP-2), CCL2 (MCP-1), CCL3 (MIP-1α), CCL4 (MIP-1β) and CCL5 (RANTES)." (PMID 34835517, 2021). "Compared to RV-A1B, RV-C15 infection induced significantly higher mRNA expression of CXCL1, CXCL2, IL-5 and IL-13." (PMID 33968043, 2021).
infection (continued). "Correlating with less pathology, we found decreased CXCL2 protein, PMN infiltrate, and bacterial plate count which was effective even when treatment was begun 6 h after infection." (PMID 34684184, 2021). "Only 4 genes overlapped both time points that also increased expression across MOIs (CXCL1, CXCL2, CXCL8 and IL6), indicating their importance as immune mediators against infection." (PMID 34001998, 2021). "Moreover, infection of the Colon Chips with the pathogenic bacterium, Salmonella typhimurium, resulted in epithelial detachment, decreased tight junction staining, and increased release of chemokines (CXCL1, CXCL2, and CCL20) that closely mimicked changes previously seen in mice." (PMID 33777849, 2021). "CXCL-2 is a member of the CXC chemokine family and plays a critical role in the recruitment of neutrophils to tissue damage, infection, and wound recovery sites." (PMID 33401552, 2021). "VSV infection significantly induced the expression of seven chemokines (CCL3, CCL4, CCL5, CCL20, CXCL1, CXCL2, and CXCL3) by ~3- to 42-fold compared to mock infection." (PMID 34578166, 2021). "Compared to sham treatment, RV-C15 infection significantly increased mRNA expression of IFN-γ, CXCL10, CXCL1, CXCL2, TNF-α, IL-12, IL-25, IL-13 and IL-5." (PMID 33968043, 2021). "Multiple factors contribute to neutrophil recruitment from the circulation to the site of infection, including proinflammatory cytokines (such as IL-1α, IL-1β, TNF-α, and IL-6) and Cxcr2 chemokines (such as Cxcl1, Cxcl2, Cxcl5, and Cxcl8)." (PMID 34011393, 2021). "After infection with E. chaffeensis, MIP-2 (CXCL2) and TNF mRNA induction in murine bone marrow derived macrophages was MyD88-dependent, but did not require TLR2 or TLR4." (PMID 33747981, 2021). "They demonstrated that the KO mice were defective in recruitment of CD11bHigh Ly6GHigh neutrophils, chemoattractants, and stabilizing factors like CXCL1, CXCL2, CCL3, and CSF3 to the site of infection in the colon." (PMID 34724858, 2021). "We also found a direct correlation in both PTB in mice with ascending infection and significant relationship between UP presence and increased TNFα, IL-1β, CXCL-1 and CXCL-2 cytokine expression in foetal membranes, placenta and the myometrium." (PMID 31924800, 2020). "NF-κB, TNF-α, and CXCL2 signaling are potential targets of XBJ and C0127s in infection-induced cardiac dysfunction." (PMID 33986658, 2020). "Gene expression analysis revealed a subset of genes, including Csf2, Cxcl1, Fas, and Cxcl2, were upregulated during T3DPL infection independently of RIG-I and/or IFN activities." (PMID 32956403, 2020). "We found a decreased expression of GRO1, CXCL2, CXCL3, and IL1A; these are all important genes for innate immunity during pathogen infection." (PMID 33374309, 2020). "Presently, the induction level of IL-1β, CXCL1 (KC), CXCL2 (MIP-2), and CCL2 (MCP-1) mRNA in the lungs after infection was significantly higher in klotho KO mice than in klotho WT mice." (PMID 33329595, 2020). "The chemokines CXCL2, CXCL3 and CXCL10 are part of “the immune response” pathway, which is highly upregulated following basolateral infection compared to control, as shown in the gene set enrichment analysis (GSEA)." (PMID 32872518, 2020). "We verified a strong upregulation of CXCL2, CXCL3, IFNλ-1, -2 and IFIT-2 genes following a basolateral infection of HIBCPP with E-30 at MOI 0.7 compared to uninfected conditions." (PMID 32872518, 2020). "Interaction between CXCL2 and CXCR2 plays an important role in the recruitment of neutrophils into infection sites." (PMID 32984356, 2020). "Using a chimeric Vi antigen insert into S. Typhimurium, this latter study showed that infection in mice not only inhibited TNF-α and CXCL2 but also increased anti-inflammatory IL-10 production." (PMID 33076485, 2020).
infection (continued). "To further study the effect of PKK depletion on lung inflammation after infection, we measured the levels of cytokines (TNFα, IL‐1β, IL‐6) and chemokines (CXCL1, CXCL2) in lung homogenates." (PMID 31595971, 2020). "To study the influence of B1R/B2R on the inflammatory response at the primary site of infection, we measured cytokine (tumor necrosis factor (TNF) α, interleukin (IL)-1β, and IL-6) and chemokine (CXCL1, CXCL2, and CCL2) levels in whole lung homogenates." (PMID 30874974, 2019). "IAV infection increased the mRNA expression at day 3 post-infection (105 PFUs) of IL-6, CCL3, CXCL2, and G-CSF, IL-1β and TNF-α (p < 0.05)." (PMID 30787331, 2019). "Chemokine expression analysis revealed that T3SS mutant induced lower mRNA levels of CXCL1, CXCL2, CXCL5, CXCL10 and CCL20 than the wild-type strain at 16 h post-infection." (PMID 30070169, 2018). "SpyCEP is a 170 kDa serine protease expressed on the surface of GAS, which proteolytically cleaves and abrogates the activities of the human chemokines CXCL1, CXCL2, CXCL6, and CXCL8/IL-8, impairing neutrophil recruitment to the site of infection." (PMID 29868516, 2018). "Infected, solvent-treated mice showed an infection-time-dependent increase in CXCL1, CXCL2 and CXCL5." (PMID 30382866, 2018). "LTB4/BLT1 axis is required for the synthesis of chemokines that recruits neutrophils (CXCL1 and CXCL2), monocytes (CCL2, CCL8, and CCL7) and T cells (CCL4) at both days 1 and 9 after infection." (PMID 30102746, 2018). "The recruitment of neutrophils into infection sites is mainly mediated by CXCR2 functioning with CXCL1 and CXCL2." (PMID 28878779, 2017). "In vivo, after G81007 infection, GLY treatment reduced clinical score and messenger RNA (mRNA) expression of IL-1β, TNF-α, CXCL2 and HMGB1." (PMID 29064403, 2017). "In this model, we also found that some genes exhibited a downward trend (e.g., Ptgs2, Rel, IL4r, CXCL1, CXCL2, TLR5, Nfatc3 and Egr2) in M. fortis after infection." (PMID 28900150, 2017). "Confirming these data, prophylactic administration of IL-22 correlated with a decrease in CXCL2 levels and PMN accumulation during infection." (PMID 28887540, 2017). "We have previously studied the cholesterol metabolism in this C. pneumoniae infection and reported tissue bacterial counts and inflammatory markers Cxcl2 and IFN-γ in the liver until day 20 of the infection." (PMID 28691023, 2017). "Despite equivalent bacterial loads, infection with tonB K. pneumoniae resulted in increased bacterial dissemination and IL-6, CXCL1, and CXCL2 secretion compared to infection with the entB ybtS tonB mutant." (PMID 27624128, 2016). "Three days post infection, CS + IAV mice had increased mRNA expression of pro-inflammatory chemokines (CCL-2, CXCL-2), cytokines (GM-CSF, TNF-α, IL-1β, IL-6) and proteases (MMP-12) compared to sham + IAV + diluent mice." (PMID 26877172, 2016). "Seven days post infection, CS + IAV mice had increased mRNA expression of pro-inflammatory chemokines (CCL-2, CXCL-2), cytokines (GM-CSF, TNF-α, IL-1β, IL-6) and proteases (MMP-12) compared to sham + IAV + diluent mice." (PMID 26877172, 2016). "Three days post infection, sham + IAV + vehicle mice had increased mRNA expression of pro-inflammatory chemokines (CCL-2, CXCL-2, CXCL-10), cytokines (GM-CSF, TNF-α, IL-1β, IL-6) and proteases (MMP-12) compared to sham + diluent + vehicle mice." (PMID 26877172, 2016). "Seven days post infection, CS + IAV mice had increased mRNA expression of pro-inflammatory chemokines (CCL-2, CXCL-2, CXCL-9, CXCL-10), cytokines (GM-CSF, TNF-α, IL-1β, IL-6) and proteases (MMP-12) compared to sham + IAV + diluent mice or CS + diluent mice." (PMID 26877172, 2016). "Only infection with the tonB mutant was sufficient to induce more secretion of IL-6, CXCL1, or CXCL2 than infection with the entB ybtS tonB (siderophore-negative) mutant, indicating that all three siderophores are required for secretion of these cytokines." (PMID 27624128, 2016).